DNMT1 (DNA methyltransferase 1)
Diseases named in the same sentence as DNMT1 in open-access papers (continued):
Sharing a sentence is not in itself a finding about the gene and the disease.
cancer (continued). "IL-6 triggers the DNMT1-mediated hypermethylation at specific promoters in cancer cell lines, that in turn increases the cellular growth rate along with other oncogenic properties." (PMID 27462204, 2016). "Evaluating the prognostic value of genetic variations in DNMT1 in the prognosis of cancer makes sense." (PMID 27087738, 2016). "To explore if DNMT1 is methylated at this lysine residue in cancer cell lines, we realised western blot with an antibody against DNMT1 K142me." (PMID 27449289, 2016). "Our results are also in good agreement with the recent finding that both de novo DNMTs showed a different pattern of expression relative to DNMT1 during carcinogenesis, with an overexpression in early cancer stages and a final reduced expression in tumors." (PMID 27129173, 2016). "TNBC is highly correlated with cancer stem cell characteristics and DNMT1 is essential for cancer cell maintenance, resulting in high expression of DNMT1 in TNBC." (PMID 27071379, 2016). "DNMT1 mediated epigenetic silencing of tumor suppressor genes contributes to the progression of cancer, which makes DNMT1 the potential target of cancer therapy." (PMID 27286455, 2016). "The inhibition of DNMT1 as a means to reactivate the expression of these silenced tumor suppressors has been proposed as a rational strategy for cancer therapy." (PMID 27525019, 2016). "Results of our studies clearly indicate that the DNMT1 protein is highly expressed in cancer tissues, and there were significant differences." (PMID 25886188, 2015). "Dnmt1 modulates DNA methylation in cancer, and Parp1 is identified to localize within the Dnmt1 promoter by PARylation." (PMID 26184161, 2015). "Multiple studies with cancer cells exposed to DNMT inhibitors have shown an inverse correlation between DNMT1 and p21 expression." (PMID 26703571, 2015). "In cancer cells, DNMT1 is responsible for the majority of the DNA-methylation capacity, and it is a contributing factor in maintaining the abnormal promoter methylation in tumor cells." (PMID 25887185, 2015). "Subsequently occurring regulatory processes can induce an aberrant stimulation of DNA methyltransferase (DNMT1) as well as changes in histone deacetylases (HDACs) and microRNAs in many cancer cell lines." (PMID 25978957, 2015). "As crucial tumor promoters and oncogenes, EZH2 and DNMT1 are highly expressed in a wide range of cancer types and overexpression of EZH2 and DNMT1 are correlated with advanced stages of cancers, resulting in poor prognosis." (PMID 26362062, 2015). "DNMT1 has been reported to be overexpressed in many cancers and to be involved in the epigenetic silencing of tumor suppressor genes in human tumor cells." (PMID 26292924, 2015). "Dysregulations of DNMT1 and aberrant DNA methylation are frequently observed in many human cancers and inhibitors for DNMT1 have been used in clinical trials for therapeutic applications." (PMID 25960197, 2015). "DNMT1, the predominant mammalian DNA methyltransferase, maintains DNA methylation and gene silencing in human cancer cells." (PMID 25863539, 2015). "For instance, mis-localization of DNMT1 in cancer cells, resulting from either impaired recruitment to replication forks, disrupted interaction with partner proteins, or translocation into a stress-induced protein complex, has been reported." (PMID 26504497, 2015). "Specific inhibition of DNMT1 or DNMT3b expression promotes growth arrest in cancer cells and attests to the relevance of DNMT expression-activity during malignant transformation." (PMID 25886188, 2015). "Recently E-cadherin expression has also been proven to be regulated by DNMT1 in different cancer cells." (PMID 25863539, 2015). "It has been reported that the anti-cancer drug 5-azacytidine (5-AZA) mediates the activation of tumor suppressor genes through passive demethylation by inhibiting DNMT1." (PMID 26366235, 2015). "One recent study notes that DNMT1 efficiency is higher in cancer cells as compared to that in normal cells." (PMID 25852822, 2015).
cancer (continued). "In cancer cells, DNMT1 is both able to maintain DNA methylation and to de novo-methylate DNA of tumour suppressor genes." (PMID 26161152, 2015). "Together, these findings suggest that in aggressive cancer cells, δEF1 recruits DNMT1 to hemi-methylated DNA in the promoter region of E-cadherin, resulting in reduced expression of E-cadherin via hypermethylation." (PMID 25315069, 2015). "It has been shown that DNMT1 is highly expressed in several cancer types and that overexpression of DNMT1 plays an important role in tumorigenesis." (PMID 25960197, 2015). "DNMT1 has been reported to regulate the expression of miRNAs in some cancers, and participate in multistage urothelial carcinogenesis." (PMID 26090723, 2015). "DNMT1 proteins are highly expressed in cancer tissues, and there were significant differences (P < 0.05)." (PMID 25886188, 2015). "Elevated expression of DNMT1 was found in various cancers including lung and antagonized the functions of tumour suppressor genes 8–10." (PMID 25598321, 2015). "Albeit this, here we have provided an important mechanism that grifolin blocks cancer cell invasion and metastasis by epigenetic regulation of DNMT1 function." (PMID 26516701, 2015). "In particular, DNMT1 is responsible for duplicating patterns of DNA methylation during replication and is essential for mammalian development and cancer cell growth." (PMID 24566147, 2014). "Tumor suppressor gene inactivation has previously been correlated with DNMT1 overexpression in various types of cancer, including hematological malignancies." (PMID 25289094, 2014). "DNMT1 alone is required to maintain a large degree of global and CpG island methylation in human cancer cells." (PMID 24987964, 2014). "Associations between SNPs of MTHFR, MTR, MTRR, DNMT1, and ALDH2 genes and cancers of the esophagus, stomach, and liver." (PMID 25337902, 2014). "KLF2 promoter is also an EZH2 target gene in many cancers and recently shown to be hyper-methylated by DNMT1 in endothelial cells." (PMID 25115397, 2014). "Decitabine normalizes the demethylation status of cancer suppressor genes by inhibition of DNA methyltransferase-1 (DNMT1), as well as normalizing terminal differentiation, the aging process or apoptosis of cells." (PMID 23599787, 2013). "DNMT1 inhibition was also tested experimentally in cancer cells by alternate pathways using HDAC inhibitors that indirectly promote ubiquitin-dependent proteasomal degradation of DNMT1." (PMID 24000324, 2013). "The link between DNMT1 hyperactivity and cancer is well established, making DNMT1 an important cancer drug target." (PMID 24236046, 2013). "Since cigarette smoke is known to modulate expression and activity of the maintenance methyltransferase DNMT1, actively dividing cells may be more susceptible to exposure-mediated defects in DNA methylation; this may in part explain the link between smoking and cancer." (PMID 23882278, 2013). "DNMT1 is a potential candidate; it has been reported to function in the role of a de novo methyltransferase in human cancer cells." (PMID 23742053, 2013). "To develop more specific DNMT inhibitors for efficient cancer therapy, we compared the effects of peptides designed to specifically disrupt the interaction of DNMT1 with different proteins." (PMID 23809695, 2013). "DNMT1 is the most abundant and methylates hemimethylated CpG di-nucleotides in the mammalian genome during DNA replication in a number of different cancer types." (PMID 24001151, 2013). "Many tumor suppressor genes became hypermethylated in cancer and a currently explanation is the increased expression of DNMT1 observed in several tumor cell lines." (PMID 24358134, 2013).
cancer (continued). "Molecular probes targeted at DNMT1 enzyme activity will also be useful in furthering our understanding of cancer etiology." (PMID 24236046, 2013). "Work in human cancer cell lines, however, demonstrated that DNMT1 can exhibit de novo methylation activity for CpG islands, and DNMT1 has been shown to be up-regulated in different tumor types." (PMID 23758948, 2013). "Several common oncogenic pathways result in the overexpression of DNMT1, either via transcriptional or post-translational mechanisms and targeting the DNMT1 isozyme for cancer therapy has been validated genetically." (PMID 24236046, 2013). "Furthermore, an association was reported between the haplotypes of DNMT1 and sensitivities to exposure of bensopyrene diol epoxide, supporting involvements of these SNPs in protecting the cell from DNA damage and reducing the intrinsic susceptibility to cancer." (PMID 23049933, 2012). "Together, these results further indicate that a combined inhibition of DNMT3B and DNMT1 is particularly effective for the demethylation of genes aberrantly hypermethylated in cancer." (PMID 22563479, 2012). "DNMT1 and DNMT3B colocalize in the nucleus, and it has been shown that in cancer cells DNMT1 and DNMT3B work cooperatively to maintain DNA methylation." (PMID 22382075, 2012). "Deregulated expression of DNMT1 is frequently observed in human tumors however its correlation with cancer progression is still object of investigation." (PMID 22305267, 2012). "5-aza-C, clinically approved to treat cancer patients, has been reported to inhibit DNMT1, 3a, and 3b in different tumors." (PMID 22870217, 2012). "In a variety of cancers, DNMT1, DNMT3a, and DNMT3b were reported to be highly expressed and associated with poor prognosis." (PMID 22768205, 2012). "Combination of HDACs and DNMT1 inhibitors exhibits synergic anti-neoplasic effect for different types of cancer." (PMID 21496237, 2011). "While Dnmt1 is considered a biological target involved in cancer development its close relative Dnmt3a, investigated in this study, has been linked to both cancer development and mental performance and health." (PMID 21510884, 2011). "Among the possible candidates, we further analyzed DNMT1, CCKBR, WNT10B, NOG and ROBO1, which are five genes whose functions have been associated with carcinogenesis or cancer development." (PMID 21205300, 2011). "In various cancer cell lines, the DNMT isoforms DNMT1 and DNMT3B are up-regulated, and as a result, the promoter region of p16INK4A is hypermethylated." (PMID 21572997, 2011). "Complete inactivation of DNMT1 led to DNA hypomethylation and mitotic catastrophe in human cancer cells." (PMID 20718950, 2010). "PcG mediated silencing is also suggested to predispose target genes to DNA-methylation in various cancers consistent with the observation that the PRC2 complex interacts with DNMT1 and DNMT3A and B." (PMID 20634887, 2010). "Aberrant CpG-island methylation in cancer is regulated by DNMT1, DNMT3A and DNMT3B which catalyze the transfer of a methyl moiety from the methyl donor S-adenosyl-L-methionine to the carbon-5 of a cytosine base." (PMID 21629434, 2010). "The Polycomb Repressive Complex 2 (PRC2), which consists of EZH2, EED and SUZ12, is necessary along with DNMT1 to maintain epigenetic silencing of the pro-apoptotic Fas gene in cancer cells." (PMID 21629434, 2010). "During DNA replication, G9a through direct interaction with DNMT1 and the DNMT1 co-factor UHRF1 coordinates the transcriptional regulation of cancer-associated genes." (PMID 21629434, 2010). "According to recent data LBH589 treatment of cancer cells leads to ubiquitin-dependent degradation of DNMT1." (PMID 20634887, 2010). "The drug also been reported preferentially depleted DNMT1, and with some specificity toward cancer cells." (PMID 20119531, 2009). "The specific inhibition of the DNA-methyltransferase DNMT1 in cancer cells was achieved by the use of a 2 ́-O-methyl thiophosphate asON MG98." (PMID 22649602, 2009).
cancer (continued). "Several previous studies have suggested that DNMT1, as a major methylation-inducing factor, is needed to maintain CpG methylation and aberrant gene silencing in human cancer cells." (PMID 18414412, 2008). "We next assessed the global changes in gene expression induced by siRNA of DNMT1 constructs or siRNA of DNMT3B constructs in hepetocellular carcinoma cell lines SMMC-7721." (PMID 27994704, 2008). "Human cancer cells differ in their reliance on DNMT1 for maintaining DNA methylation, but it is clearly required to maintain the aberrant DNA methylation in CTPE cells." (PMID 17938735, 2007). "The genetic disruption of two DNMTs, DNMT1 and DNMT3b, in a cancer cell line induces demethylation of all known hypermethylated tumour-suppressor genes and remarkably slow growth." (PMID 16404435, 2006). "DNMT1 and DNMT3b are known to catalyse DNA methylation in cancer cells; the mechanism by which DNA methylation represses gene expression is not fully understood, however, although histone deacetylation reportedly plays a key role." (PMID 15756280, 2005). "Another study using antisense and RNAi strategies suggested that Dnmt1 is responsible for global and CpG island methylation in cancer cells." (PMID 15799776, 2005). "Additionally, various therapeutic strategies, including herbal medicine, synthetic RNA molecules, DNC and miRNA replacement, have been implemented to modulate the ncRNA/DNMT1 axis as part of cancer therapy approaches." (PMID 40387409, 2025). "The reduction in DNMT1 expression may result in a relaxation of epigenetic regulations, contributing to alterations in gene expression patterns in cancer cells." (PMID 41462671, 2025). "One possible mechanism related to DNMT1/UHRF1 upregulation, leading to cancers, could be disturbed DNMT1 function due to post-translational modifications, leading to aberrant methylation activity." (PMID 40558829, 2025). "In addition to the bioinformatic analyses, this antagonistic relationship was further confirmed by IF experiments in hypomethylated cancer tissues, DNMT1 knockout cells, and cells treated with methylation inhibitors." (PMID 40646558, 2025). "This study demonstrates that FVTF substantially decreased in vitro and in vivo stemness of HCC cells through the downregulation of DNMT1, indicating that FVTF may be a promising anti-cancer agent via targeting DNMT1." (PMID 40050970, 2025). "We inferred the following mechanism: 1) Proliferating cancer cells in the breast duct secret DNMT1; 2) The secreted DNMT1 passes through breast duct and enters the circulating system; 3) Higher tumor burden results in increased DNMT1 secretion, which can then be detected in plasma." (PMID 40317882, 2025). "Recent studies suggest a potential relationship between MLH1 and DNMT1 that may influence tumor antigenicity, triggering immune responses that can target and eliminate cancer cells." (PMID 39996888, 2025). "It is proposed that elevated levels of DNMT1 in cancer cells may lead to the downregulation of MLH1, resulting in an overall decrease in tumor antigenicity." (PMID 39996888, 2025). "Notably, TNF-α-induced phosphorylation of RelA at serine 276 in certain cancer cells facilitates the recruitment of DNA methyltransferase 1 (Dnmt1) to tumor suppressor genes (e.g., BRMS1)." (PMID 40562870, 2025). "In addition, the ncRNA‐DNMT1 axis plays a crucial role in regulating CSCs activity, with multiple microRNAs, such as miR‐34a and miR‐126, modulating DNMT1 expression to influence stemness characteristics and tumour progression across various cancers." (PMID 40387409, 2025). "Zinc deficiency increased the expression and activity of DNMT1 and DNMT3A in human cancer cell lines and upregulated DNMT1 and downregulated DNMT3A in the hippocampus of cognitive dysfunction murine models, wherein these DNMT alterations were significantly mitigated by zinc supplementation." (PMID 39941940, 2025).
cancer (continued). "Notably, the inhibition of either DNMT1 or BCL11A results in a compromised capacity for cancer stemness and tumorigenesis in TNBC, which is achieved through the suppression of ISL1 expression both in vivo and in vitro." (PMID 40387409, 2025). "Furthermore, we discuss the important role of the ncRNAs‐DNMT1 axis in cancer stem cells and cancer therapy resistance as critical issues in cancer therapy." (PMID 40387409, 2025). "Furthermore, TIMP3, recognized as a tissue inhibitor of metalloproteinases and important for extracellular matrix remodeling, is often transcriptionally silenced in cancer cells due to DNA methylation driven by DNMT1." (PMID 39996888, 2025). "Additionally, curcumin interacts with DNMT1’s catalytic thiolate to target the enzyme directly, diminishing methylation in various cancer models." (PMID 40663150, 2025). "This study examines the expression levels of certain proteins (DNMT1, DNMT3A, and DNMT3B) in tumor tissue, using immunohistochemistry to assess whether these protein levels are linked to the risk of cancer recurrence or mortality." (PMID 40507223, 2025). "Given DNMT1’s pivotal role in maintaining aberrant methylation in cancer cells, it has emerged as a critical target for therapeutic interventions against epigenetic stability of tumorigenesis, as altered DNA methylation can contribute to cancer progression." (PMID 39996888, 2025). "DNA Methyltransferases (DNMT1, DNMT3a/3b) contribute to aberrant methylation patterns in cancer." (PMID 40650308, 2025). "Moreover, the results of Northern blot and RT-PCR assays indicated that DNMT1 expression increases in human cancer cells and patients with colonic neoplasia." (PMID 41226543, 2025). "extracts reduce the expression of DNA methyltransferase 1 (DNMT1) in human cancer cells." (PMID 41516084, 2025). "This occurs through the downregulation of DNA methyltransferases DNMT1, DNMT3A, and DNMT3B, and the upregulation of Methyl CpG Binding Domain Protein 2 (MBD2), a marker often associated with cancer due to its role in causing genomic instability and increasing mutation frequencies." (PMID 39829957, 2025). "Since cellular senescence is involved in aging, tissue degeneration, and cancer, modulating DNMT1, SPINT2, and c-Met signaling could provide novel therapeutic opportunities." (PMID 40838961, 2025). "To further elucidate the mechanisms behind increased DNMT1 activity in plasma and its potential sources, we analyzed tissue microarray of 59 patients and evaluated the DNMT1 expression intensity in cancer regions and paired adjacent tissue using immunohistochemistry (IHC)." (PMID 40317882, 2025). "Also, DNMT1/miR‐34a axis plays a crucial role in regulating osteosarcoma cancer stem‐like cells (OSLCs)." (PMID 40387409, 2025). "One of these, UHRF1/2, recruits DNMT1 to hemimethylated DNA, and its overexpression plays a role in the silencing of tumor suppressor genes, as well as in migration, proliferation, and metastasis in various cancers." (PMID 40558829, 2025). "Finally, we demonstrate that herbal medicine and synthetic RNA molecules regulate DNMT1 activity and hold great promise in cancer treatment." (PMID 40387409, 2025). "Furthermore, miR‐137 disrupts the interaction between BCL11A and DNMT1, reducing cancer stemness and inhibiting tumour progression in TNBC." (PMID 40387409, 2025). "Aberrant methylation can silence tumor suppressor genes, and inhibition of DNMT1 by these complexes may restore their expression, thereby suppressing cancer cell proliferation." (PMID 40575462, 2025). "The effect of DNA methyltransferase (DNMT) 1 gene status on TET2 expression following DNMT inhibitor treatment remains unknown in cancer." (PMID 39057134, 2024). "Similarly, MGMT-DPCs formed following cellular treatment with N-methyl-2,2-di(chloroethyl)amine and DNMT1 DPCs formed in various cancer cell lines treated with aza-dC were shown to be SUMOylated." (PMID 38254974, 2024).